RNU6-812P (RNA, U6 small nuclear 812, pseudogene)
Gene: Small nuclear RNA gene on chromosome 2 (78,882,628 to 78,882,734, forward strand). Ensembl gene ENSG00000200048.
Homologues: Orthologues: chimpanzee U6 (98% identical), dog U6 (91% identical), rabbit U6 (88% identical), zebrafish U6 (78% identical), macaque U6 (73% identical). Paralogues in human: RNU6-211P (93% identical), RNU6-11P (92% identical), RNU6-20P (92% identical), RNU6-37P (92% identical), RNU6-1145P (91% identical), RNU6-1152P (91% identical), RNU6-16P (91% identical), RNU6-25P (91% identical), RNU6-35P (91% identical), RNU6-38P (91% identical), RNU6-393P (91% identical), RNU6-41P (91% identical), and 1288 more.